APPL1 (adaptor protein, phosphotyrosine interacting with PH domain and leucine zipper 1)
Diseases named in the same sentence as APPL1 in open-access papers (continued):
Sharing a sentence is not in itself a finding about the gene and the disease.
Alzheimer disease (8 papers, 2011 to 2025). A progressive, neurodegenerative disease characterized by loss of function and death of nerve cells in several areas of the brain leading to loss of cognitive function such as memory and language. "Moreover, endocytosis mediated by APPL1/Rab5 constitutes a novel APP-dependent pathogenic pathway in Alzheimer’s disease (AD) and APPL1 has also been found to accumulate as granules around neurons in postmortern human brain of AD." (PMID 33104190, 2021).
Obesity (6 papers, 2012 to 2022). Accumulation of substantial excess body fat. "The actions of APPL1 in immune cells prevent obesity-associated metabolic disorders and endotoxin-induced sepsis." (PMID 34789781, 2021). "APPL1 deficiency in hematopoietic cells exacerbates obesity-induced chronic inflammation and endotoxin-induced septic shock in animal models." (PMID 34789781, 2021). "Mice deficient for APPL1 specifically in hematopoietic cell are more sensitive to endotoxin-induced sepsis, obesity-induced inflammation and glucose dysregulation." (PMID 34789781, 2021). "In vitro, we tested whether APPL1 deficiency has any effect on inflammasome activation induced by palmitic acid, the most abundant saturated fatty acid with marked elevation in obesity and is known to induce NLRP3 inflammasome activation by inhibiting autophagy/mitophagy." (PMID 34789781, 2021). "In obesity conditions, APPL1 interaction with insulin receptors is diminished, whereas the interaction between APPL1 with adiponectin receptors promotes activation of AMP-activated kinase (AMPK), favoring insulin sensitivity." (PMID 35409282, 2022). "The data of the present study indicate that endometrial APPL1 levels were lower in women with obesity and obesity plus PCOS (both with IR condition, p < 0.05)." (PMID 35409282, 2022). "Collectively, these findings reveal that APPL1 in immune cells is crucial for preventing obesity- and LPS-induced inflammation, perhaps, by promoting mitophagy." (PMID 34789781, 2021). "In vivo, we demonstrated that hematopoietic APPL1 is crucial to restrict NLRP3 inflammasome activation in obesity and acute septic response." (PMID 34789781, 2021). "Previous studies have demonstrated a significant association between APPL1 gene variants and body fat distribution in T2DM and a significant association of APPL2 genetic variation with overweight and obesity." (PMID 23977033, 2013). "Additionally, it has been determined that serum levels of adiponectin and endometrial levels of APPL1 in patients with PCOS with obesity, hyperandrogenism and hyperinsulinism are diminished." (PMID 35409282, 2022). "Moreover, it was observed that key downstream regulatory molecules associated with adiponectin signaling, such as APPL1 and APPL2, are altered in endometria from women with obesity and IR, with or without PCOS." (PMID 35409282, 2022).
type 2 diabetes (6 papers, 2012 to 2025). "Recently, it was found that APPL1 mutations can cause maturity onset diabetes of the young, type 14." (PMID 32854233, 2020). "Our previous study has demonstrated that genetic variants of APPL1 are correlated with body fat distribution in Chinese type 2 diabetic patients." (PMID 22462604, 2012).
Hyperglycemia (5 papers, 2015 to 2021). An increased concentration of glucose in the blood. "Although we have recently reported that in one of our families a severe mutation in the APPL1 gene causes hyperglycemia, further studies are needed to unravel and dissect the whole genetic background of FDA." (PMID 26287533, 2015). "In conclusion, this work demonstrated that 20 mg/kg THC ameliorated hyperglycemia in HFD/STZ-induced diabetic obese mice by restoring adiponectin, adiponectin receptors, and APPL1, further improving metabolic homeostasis in the liver and muscle as well as β-cell function." (PMID 34960104, 2021).
myocardial ischemia (3 papers, 2021 to 2024). A disorder of cardiac function caused by insufficient blood flow to the muscle tissue of the heart. "Consistent with the observation in myocardial ischemia tissues, the results from RT-qPCR and western blotting showed that hypoxia-reperfusion treatment caused a reduction in APPL1 expression in H9C2 cells when compared with control group." (PMID 34304702, 2021). "Hence, the aim of the present study was to investigate the specific mechanism underlying the role of APPL1 in myocardial ischemia." (PMID 34304702, 2021). "Interaction between ADIPOR1 and APPL1 diminishes the cardioprotective effects of adiponectin on myocardial ischemia/reperfusion injury in type 2 diabetic mice." (PMID 38049739, 2023). "Taken together, APPL1 knockdown suppressed the viability of myocardial ischemia cells and aggravated hypoxia/reperfusion-induced LDH hypersecretion, inflammation and apoptosis, which was, to our interest, abrogated by APAF1 inhibitor." (PMID 34304702, 2021). "We conclude that APPL1 inhibits myocardial ischemia/hypoxia-reperfusion injury via inactivation of APAF-1/Caspase9 signaling pathway." (PMID 34304702, 2021). "APPL1 knockdown suppressed the viability of myocardial ischemia cells and aggravated hypoxia/reperfusion-induced LDH hypersecretion, inflammation and apoptosis." (PMID 34304702, 2021). "Our findings demonstrated that APPL1 was low expressed in myocardial ischemia tissues and cells." (PMID 34304702, 2021). "In our study, the APPL1 expression was significantly reduced in cellular H/R model and the myocardial tissue of I/R injury mice model, suggesting APPL1 was closely related to pathogenesis of myocardial ischemia." (PMID 34304702, 2021). "However, there are few studies on the role of APPL1 in myocardial ischemia." (PMID 34304702, 2021). "Hence, the present study aimed to explore the role of APPL1 in myocardial ischemia." (PMID 34304702, 2021). "However, it is unclear whether APPL1 could contribute to the onset and development of myocardial ischemia." (PMID 34304702, 2021). "Hence, APPL1 may be presented as a novel and effective target for the treatment of myocardial ischemia." (PMID 34304702, 2021). "Hence, APPL1 may be a novel and effective target for the treatment of myocardial ischemia." (PMID 34304702, 2021). "However, the role of APPL1 in myocardial ischemia remains unclear." (PMID 34304702, 2021). "The ensuing finding that APPL1 knockdown led to higher cell apoptosis rates and increased the protein levels of pro-apoptotic-proteins, Bax and cleaved PARP, and reduced anti-apoptosis protein Bcl-2 protein levels that participated in the apoptosis induced by myocardial ischemia/reperfusion." (PMID 34304702, 2021).
osteoporosis (3 papers, 2022 to 2025). A condition of reduced bone mass, with decreased cortical thickness and a decrease in the number and size of the trabeculae of cancellous bone (but normal chemical composition), resulting in increased fracture incidence. "This study aimed to investigate the role of APPL1 in the osteogenic differentiation of MSCs in osteoporosis and the underlying regulatory mechanism." (PMID 37187293, 2023). "Our previous study verified that Adaptor protein, phosphotyrosine interacting with PH domain and leucine zipper 1 (APPL1)/myoferlin deficiency promotes adipogenic differentiation of MSCs by blocking autophagic flux in osteoporosis." (PMID 37187293, 2023). "Our previous study verified that APPL1/myoferlin deficiency promotes adipogenic differentiation of MSCs by blocking autophagic flux in osteoporosis." (PMID 37187293, 2023). "In this study, we aimed to explore the mechanism underlying the role of APPL1 in the abnormal balance of hMSC adipogenic and osteogenic differentiation in osteoporosis." (PMID 35984564, 2022). "Our previous studies have shown that APPL1 deficiency occurs in osteoporosis and that APPL1 plays a critical role in regulating hMSCs adipogenic differentiation." (PMID 35984564, 2022). "In addition, the severity of clinical osteoporosis was negatively correlated with the expression of APPL1 in bone marrow MSCs, and overexpression of APPL1 in osteoporotic mice significantly alleviated bone loss." (PMID 37187293, 2023). "Taken together, these findings suggest that APPL1 significantly reduced bone mass loss in GIOP mice and that APPL1 may be an important target for the diagnosis and treatment of osteoporosis." (PMID 37187293, 2023). "APPL1 deficiency in osteoporosis was first revealed in our study, and we propose that APPL1 deficiency is an important molecular mechanism that causes the hMSCs adipogenic-osteogenic differentiation balance to shift towards the adipocyte lineage in individuals with osteoporosis." (PMID 35984564, 2022). "Overall, our study might more accurately clarify the role and underlying mechanism of APPL1 in the abnormal balance of hMSC adipogenic-osteogenic differentiation in patients with osteoporosis." (PMID 35984564, 2022). "In this study, we demonstrated that APPL1 reduced glucocorticoid-induced bone loss by promoting osteogenic differentiation of MSCs in vivo, and we emphasized that our animal model of osteoporosis can be used to investigate osteogenic differentiation of osteoporosis." (PMID 37187293, 2023). "Furthermore, an APPL1-overexpressing adenovirus was injected into osteoporotic mice, and the expansion of bone marrow adipose tissue and bone mass loss were diminished that osteoporosis symptoms were relieved, suggesting that strategies targeting APPL1 in hMSCs are effective in osteoporotic therapy." (PMID 35984564, 2022). "In this study, we demonstrated the downregulation of APPL1 expression in patients with osteoporosis and osteoporosis mice." (PMID 37187293, 2023). "Our previous study showed that the expression of APPL1 was downregulated in osteoporosis and that the impairment of APPL1/myoferlin facilitates adipogenic differentiation of MSCs by blocking autophagic flux." (PMID 37187293, 2023). "Mechanistically, reduced APPL1 impaired the osteogenic differentiation of MSCs by facilitating MGP expression to disrupt the BMP2 pathway in osteoporosis." (PMID 37187293, 2023). "The severity of clinical osteoporosis was negatively correlated with the expression of APPL1 in bone marrow MSCs." (PMID 37187293, 2023). "Mechanistically, our study showed that reduced APPL1 impaired the osteogenic differentiation of mesenchymal stem cells by facilitating Matrix Gla protein expression to disrupt the BMP2 pathway in osteoporosis." (PMID 37187293, 2023). "In the current study, we confirmed that APPL1 expression was decreased in osteoporosis and positively regulated the osteogenic differentiation of MSCs." (PMID 37187293, 2023).
osteoporosis (continued). "Our previous study has shown that the impairment of APPL1/myoferlin facilitates adipogenic differentiation of MSCs by blocking autophagic flux in osteoporosis." (PMID 37187293, 2023). "To further clarify the role of APPL1 in osteogenesis in osteoporosis, we successfully established a mouse model of glucocorticoid-induced osteoporosis (GIOP)." (PMID 37187293, 2023). "The concentration of APPL1 decreased significantly in patients with osteoporosis and was positively correlated with the T-score." (PMID 37187293, 2023). "We also evaluated the significance of APPL1 in promoting osteogenesis in a mouse model of osteoporosis." (PMID 37187293, 2023). "In this study, we found that APPL1 was able to enhance osteogenic differentiation of MSCs in vitro and reduced glucocorticoid-induced bone loss in vivo, highlighting its potential use may be an alternative drug to treat osteoporosis by modulating osteogenic differentiation." (PMID 37187293, 2023). "On the other hand, clinical trials are needed to further explore the application of APPL1 in osteoporosis." (PMID 37187293, 2023). "Here, we found that APPL1 expression was downregulated in elderly patients with osteoporosis and in mouse osteoporosis model." (PMID 35984564, 2022). "In summary, APPL1 plays an important role in maintaining the balance of hMSC adipogenic-osteogenic differentiation in osteoporosis, providing a potential target for osteoporosis diagnosis and treatment." (PMID 35984564, 2022). "Because the elderly osteoporosis model has a long construction period, an assessment of treatment efficacy is difficult; therefore, a murine postmenopausal osteoporosis model was used in our studies to examine the effect of APPL1 on osteoporosis." (PMID 35984564, 2022). "APPL1 overexpression in a mouse osteoporosis model successfully inhibited adipose tissue growth and alleviated bone loss." (PMID 35984564, 2022). "Finally, we recruited ten patients with osteoporosis and ten healthy volunteers to determine the relationship between the severity of osteoporosis and APPL1." (PMID 37187293, 2023). "In conclusion, we identified APPL1 may be an important regulator in osteoporosis, which inhibited the expression of MGP, activated the BMP2 pathway, and promoted the osteogenic differentiation of MSCs." (PMID 37187293, 2023). "Moreover, APPL1 overexpression effectively alleviated osteoporosis and promoted osteogenic differentiation of MSCs, whereas APPL1 knockdown attenuated osteogenic differentiation of MSCs." (PMID 37187293, 2023). "Besides, the severity of clinical osteoporosis was negatively correlated with APPL1 expression in bone marrow MSCs." (PMID 37187293, 2023). "In this study, we found that APPL1 expression was downregulated in osteoporosis patients and mice." (PMID 37187293, 2023). "Combined with our previous study, it suggests that APPL1 may be an important molecule leading to the abnormal balance of adipogenic and osteogenic differentiation of MSCs in osteoporosis." (PMID 37187293, 2023). "Further study of the APPL1 molecular mechanism in hMSCs may contribute to its development as a potential target for the diagnosis and treatment of osteoporosis through hMSC tissue engineering." (PMID 35984564, 2022). "By comparing APPL1 expression levels between the control group and osteoporosis group, we hypothesized that the occurrence and development of osteoporosis are closely related to the downregulation of APPL1 expression." (PMID 35984564, 2022). "To explore the potential of APPL1 to target osteoporosis, we constructed a mouse model of osteoporosis to investigate whether the progression of osteoporosis would be halted by modifying APPL1 levels in mice." (PMID 35984564, 2022). "The upstream regulatory mechanism by which APPL1 expression is reduced in individuals with osteoporosis remains unclear." (PMID 35984564, 2022). "Therefore, we assumed that the occurrence of osteoporosis is also related to APPL1 expression levels." (PMID 35984564, 2022).
osteoporosis (continued). "Therefore, we aimed to explore the mechanisms by which APPL1 alters hMSCs adipogenic differentiation in osteoporosis." (PMID 35984564, 2022). "Therefore, our study suggested that APPL1 may be an important target for the diagnosis and treatment of osteoporosis." (PMID 37187293, 2023). "However, the role of APPL1 in the imbalance of hMSC differentiation in osteoporosis is unclear." (PMID 35984564, 2022). "Therefore, to further investigate whether APPL1 can be a target for osteoporosis treatment, an APPL1-overexpressing adenovirus was injected into a mouse osteoporosis model in our study." (PMID 35984564, 2022). "In this study, we identified five key genes related to the circadian rhythm in osteoporosis (RAB5C, ECE1, FLT3, FCGR2A, and APPL1) using bioinformatics and machine learning approaches." (PMID 40642528, 2025). "The role of APPL1 in osteoporosis has not been reported in recent studies; therefore, we examined APPL1 expression levels in elderly patients with osteoporosis and a mouse osteoporosis model." (PMID 35984564, 2022). "Thus, the APPL1/MYOF axis may be a promising target for the clinical diagnosis and treatment of osteoporosis." (PMID 35984564, 2022). "However, the role of APPL1 in osteoporosis has not yet been elucidated." (PMID 37187293, 2023).
brain ischemia (2 papers, 2021 to 2022). Diminished or absent blood supply to the brain caused by obstruction (thrombosis or embolism) of an artery resulting in neurologic damage. "Emerging evidence has implied that APPL1 was involved in the pathology of renal ischemia and brain ischemia." (PMID 34304702, 2021). "However, AdipoRon pretreatment attenuated the cerebral ischemia–induced injury in both DDAH1−/− and DDAH1+/+ rats and also enhanced the APR1/APPL1/pAMPK signaling." (PMID 35509834, 2022).
diabetic cardiomyopathy (2 papers, 2016 to 2024). Diabetic cardiomyopathy is a disorder of the heart muscle in people with diabetes. "APPL1 is known to protect against cardiomyocyte senescence, cardiac fibrosis, and diabetic cardiomyopathy." (PMID 38664788, 2024). "However, the mechanism of APPL1 activity is unclear, and there is little research about the role of APPL1 in diabetic cardiomyopathy and cardiomyocyte apoptosis." (PMID 26759813, 2016).
glioma (2 papers, 2013 to 2016). A benign or malignant brain and spinal cord tumor that arises from glial cells (astrocytes, oligodendrocytes, ependymal cells). "APPL1 and APPL2 have been linked to cell survival in vertebrate development and in human glioma cells." (PMID 26583432, 2016).
hypoadiponectinemia (2 papers, 2013 to 2022). "ZDF rats also exhibit hypoadiponectinemia and a suppressed expression of APPL1, an adaptor protein of the adiponectin receptors, in mesenteric resistance arteries." (PMID 23497197, 2013). "Interestingly, a study has shown that MTF (or insulin) inhibits the development of hypoadiponectinemia and prevents the downregulation of APPL1 in mesenteric resistance arteries." (PMID 35409282, 2022). "As possible pathological mechanism we found hypoadiponectinemia in ZDF rats and a downregulation of APPL1 in their mesenteric arteries at mRNA level." (PMID 23497197, 2013). "An antidiabetic treatment with either insulin or metformin in ZDF rats inhibits the development of hypoadiponectinemia and downregulation of APPL1 in mesenteric resistance arteries, but is not able to improve adiponectin induced vasodilation and endothelial dysfunction." (PMID 23497197, 2013).
ischemia (2 papers, 2021 to 2022). A hypoperfusion of the BLOOD through an organ or tissue caused by a PATHOLOGIC CONSTRICTION or obstruction of its BLOOD VESSELS, or an absence of BLOOD CIRCULATION. "APPL1 acts as an immediate downstream effector of APR1 to mediate APN-induced phosphorylation of AMPK, which plays a protective role in brain damage after ischemia." (PMID 35509834, 2022).
lung adenocarcinoma (2 papers, 2013 to 2016). A carcinoma that arises from the lung and is characterized by the presence of malignant glandular epithelial cells. "APPL1 and Rab5a have recently been found to be overexpressed in lung adenocarcinoma, but the precise role of APPL proteins in malignancies is still unknown." (PMID 26583432, 2016). "Some of the genes such as PIK3CA, TAF15, VAPB, Appl1, Rab5a, ARF4, and XIAP in Merged-module activate the PI3K-Akt pathway and are overexpressed in a manner similar to that of EGFR in lung adenocarcinoma." (PMID 23874428, 2013).
neuroblastoma (2 papers, 2018 to 2019). Neuroblastoma (NB) is the most common solid, extracranial childhood tumor. "APN is protective against cytotoxicity of human neuroblastoma cells (SH-SY5Y) expressing mutant APP (Sw-APP) under oxidative stress through APPL1-mediated AMPK activation, associated with suppression of NF-κB activation." (PMID 31128596, 2019). "Our previous study reported that APN protected SH-SY5Y neuroblastoma cells overexpressing AβO from cytotoxicity under oxidative stress and it was through APPL1-mediated AMPK activation that suppressed the NF-κB activation." (PMID 31128596, 2019).
Non-Alcoholic Fatty Liver Disease (2 papers, 2013 to 2021). "The aim of our study will be the evaluation of a potential association between the APPL1 and APPL2 loci and the occurrence and progression of non alcoholic fatty liver disease (NAFLD)." (PMID 23977033, 2013).